IL27 (interleukin 27)
Diseases named in the same sentence as IL27 in open-access papers (continued):
Sharing a sentence is not in itself a finding about the gene and the disease.
Arthritis (continued). "Thus, IL-27 suppresses osteoclastogenesis and inflammatory cytokine production and inhibits arthritis development." (PMID 38566992, 2024). "The addition of IL-27 into IL-23-induced arthritis mice ameliorated disease incidence and disease severity, inhibited neutrophil proliferation and γδ T-cell accumulation, and resulted in reduction in serum levels of IL-6, IL-17, and IgG2a, and percentage of cells expressing IL-17 and IFNγ." (PMID 38566992, 2024). "Moreover, the addition of IL-27 at the onset of adjuvant-induced arthritis was able to inhibit joint inflammation; however, if IL-27 was added in a later phase, it will promote the inflammation process." (PMID 38566992, 2024). "IL-27 has both an anti-inflammatory and pro-inflammatory role in arthritis." (PMID 38566992, 2024). "For example, IL-27rα−/− mice were protected against arthritis, whereas the addition of IL-27 to collagen- and osteocollagenesis-induced arthritis may inhibit arthritis development." (PMID 38566992, 2024). "In a different investigation, IL-27 therapies mitigated the severity of arthritis in mice with CIA." (PMID 39766196, 2024). "The present work initiated a road to discovery of new targeted IL-27 molecules that may be able to enhance low-dose RA therapies and may be applicable to other arthritis types." (PMID 35735491, 2022). "Prior work from our group indicated promise for IL-27 in modulating pathways that could aid in arthritis treatment." (PMID 35735491, 2022). "The intra-articular overexpression of IL-27 also attenuates arthritis severity in CIA mice." (PMID 35058928, 2021). "Although it is unknown how exogenous IL-27 affects the progression of RA patients, validation from an arthritis animal model could help to clarify this." (PMID 35058928, 2021). "It was further shown that IL-27 itself inhibited γδ T cells and reduced IL-23 induced arthritis." (PMID 32085540, 2020). "IL-27 has key functions in bone repair, helping prevent osteoclast formation and promoting osteoblast differentiation, and these features can be used to treat various forms of arthritis as well as bone-metastatic tumors." (PMID 32046108, 2020). "In an arthritis model, IL-27 attenuates disease development and histological disease severity (i.e., cell infiltration in the joint, synovial hyperplasia, and joint erosion) by reducing the expansion of Th17 cells and IL-17 levels, which can reduce nociception." (PMID 32047493, 2019). "Our results suggest that further exploration of the mechanistic role of IL-27 in the context of arthritis flare may prove valuable." (PMID 31280933, 2019). "Furthermore, IL-27 gene transfer prior IL-23 MC injection inhibits arthritis development and both neutrophils and γδ T cell expansion." (PMID 29765156, 2018). "In this study, we identified a molecular interplay between IL-27, γδ T cells and neutrophils suggesting that IL-27 could be the mechanism by which γδ T cell regulates neutrophil expansion and subsequently impact arthritis development." (PMID 29765156, 2018). "Furthermore, we reported that IL-27 is able to suppress IL-23-induced arthritis through limiting neutrophil expansion and migration velocity as well as γδ T cell accumulation." (PMID 29765156, 2018). "Next, we investigated whether increased IL-27 production affect the development of IL-23-induced arthritis." (PMID 29765156, 2018). "In addition, recent studies have correlated IL-27 levels with the morbidity of multiple sclerosis, arthritis, and experimental models of disease mediated by Th17 cells." (PMID 29033934, 2017). "However, Fc-IL27 was a partially effective system, with arthritis incidence reductions of ~50% and Th17 reductions of ~40%." (PMID 28265470, 2017). "However, in another experimental arthritis model of proteoglycan-induced arthritis, it appears that IL-27 played a pro-inflammatory role." (PMID 27687913, 2016).
Arthritis (continued). "Hence, a high dose of IL-27 administered daily could effectively inhibit both intestinal inflammation and arthritis, the two main pathologic features in this rat model of SpA." (PMID 36818477, 2022). "However, IL-27 treatment worsens arthritis in proteoglycan-induced arthritis (PGIA) mice." (PMID 35058928, 2021). "However, IL-27 MC injection prior IL-23 MC gene transfer significantly ameliorated both disease incidence and disease severity in the IL-23-induced arthritis." (PMID 29765156, 2018). "The findings suggested that IL-27 may inhibit the effects of TNFα, IL-17, RANKL, and IL-23, and then suppress arthritis development." (PMID 38566992, 2024). "Ectopic lymphoid structures substantially increase in quantity and severity in experimental arthritis in the absence of IL-27." (PMID 39766196, 2024). "We showed that intravenous injection of liposomes displaying this peptide and entrapping an experimental biologic, interleukin-27 (IL-27), was more effective in inhibiting arthritis than IL-27-entrapping liposomes lacking this peptide." (PMID 37108047, 2023). "In the first experiment, arthritis course was not significantly affected by IL-27 treatment, whereas the second more intense regimen of rrIL-27 administration was associated with inhibition of arthritis development." (PMID 36818477, 2022). "In an arthritis model, IL-27 treatment affected the expression of IL-17 but not Foxp3 in CIA mouse spleens." (PMID 35058928, 2021). "While interleukin-27 (IL-27) which is in the same family as IL-23, plays a significant role in bone remodeling and arthritis, its role in axial spondyloarthropathies in vivo has not been investigated in vivo especially in the absence of arthritic triggers." (PMID 29494633, 2018). "A recent report used subcutaneous delivery of Fc-IL27 to confirm its high promise for controlling collagen-induced arthritis through reducing Th17 proinflammatory cells without systemic toxicity." (PMID 28265470, 2017). "Similar differences were also observed in an arthritis model: in a CIA model administration of IL27 systemically improves the clinical score, while in a proteoglycan-induced arthritis model the lack of WSX1 also improves the clinical scores." (PMID 21559505, 2011). "Evidences from arthritis animal models suggests that rather than a bystander, IL-27 may also be involved in the progression of RA." (PMID 35058928, 2021).
atherosclerosis (30 papers, 2012 to 2025). A disease characterized by the build-up of fatty material and calcium deposition in the arterial wall resulting in partial or complete occlusion of the arterial lumen. "Atherosclerosis is a progressive arterial disease characterized by chronic inflammation, with interleukin-27 (IL-27) implicated as both a pro- and anti-inflammatory cytokine." (PMID 41302192, 2025). "IL-27 gene polymorphisms have been linked to increased cardiometabolic risk, and preclinical and premature atherosclerosis." (PMID 41302192, 2025). "Genetic studies support this dual role of IL-27, with polymorphisms in the IL-27 gene being associated with insulin resistance and subclinical atherosclerosis in T2DM." (PMID 39906735, 2024). "Genetic mutations in the IL-27 p28 subunit enhance its inflammatory potential, as seen in early-onset atherosclerosis and Kawasaki disease patients with the rs17855750 variant, which predisposes individuals to coronary artery disease." (PMID 39906735, 2024). "CT-1 deficiency in advanced atherosclerosis mediated regulation of paracrine factors, such as interleukin (IL)-3, IL-6, IL-9, IL-15, IL-27, CXCL5, MCP-3, MIP-1α and MIP-1β." (PMID 32238841, 2020). "IL-27 has been implicated in the endothelial dysfunction that occurs during cardiovascular pathology central to atherosclerosis by stimulating inflammatory cytokine and chemokine expression." (PMID 31818960, 2020). "In the murine model, IL-27 administration suppressed macrophage activation and atherosclerosis development and mice deficient for IL-27 or its receptor showed increased atherosclerosis susceptibility, suggesting IL-27 has a protective role." (PMID 28969085, 2017). "Despite all the evidence on the role of IL-27 in atherosclerosis, to best of our knowledge, to date only one cross sectional analysis has evaluated the role of IL-27p28 gene variants in cardiovascular disease." (PMID 28969085, 2017). "Treatments that target interleukins, such as IL-27, IL-28, IL-29, IL-31, IL-32, and IL-33, have shown promise in reducing fibrosis and inflammation, two important processes linked to the development of heart disorders such as atherosclerosis and heart failure." (PMID 39844544, 2025). "IL-27-deficient mice also developed increased atherosclerosis with enhanced macrophage activation." (PMID 38786961, 2024). "Thus, the hyperlipidemia‐IL‐27‐Tfh cell axis might be a probable mechanism in atherosclerosis‐associated SLE in both mice and humans." (PMID 33230950, 2020). "In atherosclerosis, IL-27 has been primarily identified as a pro-atherosclerotic cytokine, by promoting adhesion molecule upregulation in endothelial and CD4+ T cells." (PMID 41302192, 2025). "Conversely, elevated circulatory levels of IL-27 seem to represent an unfavorable finding in patients with atherosclerosis." (PMID 41302192, 2025). "By interfering with the differentiation of Th17 cells, IL-27 helps to control the inflammatory response, ultimately influencing the progression of conditions like atherosclerosis." (PMID 39844544, 2025). "In contrast, in animal models of atherosclerosis, recombinant IL-27 administration inhibited the progression of atherosclerosis in ApoE-deficient mice." (PMID 38786961, 2024). "As for blood IL-27 levels and atherosclerosis, plasma lL-27 levels were reported to be higher in 140 patients who had carotid artery stenosis compared with 19 healthy controls." (PMID 38786961, 2024). "In obesity and dyslipidemia, IL-27 promotes the activation of macrophages and Th1 cells, contributing to the chronic inflammation in adipose tissue and the progression of atherosclerosis." (PMID 39906735, 2024).
atherosclerosis (continued). "Regarding the role of IL-27 in atherosclerosis, IL-27 enhanced the upregulation of adhesion molecules and pro-inflammatory cytokines in cultured endothelial cells." (PMID 38786961, 2024). "We also observed that DCs treated with IL-27 display a tolerogenic phenotype and that IL-27–treated tolerogenic DCs (tDCs) are likely to play a protective role during atherosclerosis." (PMID 36405994, 2022). "In summary, our study is the first to highlight that LAP+ Tregs play a crucial role in the IL-27 signaling that limits atherosclerosis." (PMID 36405994, 2022). "Compared with the mice treated with PBS, the mice treated with IL-27 during the progression of atherosclerosis displayed a reduction of 24.4% in aortic sinus atherosclerotic lesion size (605.7 ± 38 × 103 μm2 vs 457.8 ± 37 × 103 μm2, respectively; P = 0.02)." (PMID 36405994, 2022). "In our research, we examined the influence of the administration of IL-27 and an anti-IL-27p28 antibody (anti-IL-27p28-Ab) on both the initiation and the progression of atherosclerosis." (PMID 36405994, 2022). "We have further observed that IL-27-tDCs induce a tolerogenic immune response and alleviate atherosclerosis in ApoE−/− mice." (PMID 36405994, 2022). "We reported that the administration of IL-27 prevents both the initiation and the progression of atherosclerosis by inducing LAP+ and Foxp3+ Tregs." (PMID 36405994, 2022). "In the HIVneg group, IL-27, IL-17C and CCL26 remained significantly associated with subclinical atherosclerosis following the regression analysis (p=0.041, p=0.012 and p=0.016, respectively), whereas IL-32θ and TNF-α were no longer significant." (PMID 33936102, 2021). "Together these findings point to a potential role for IL-27 in atherogenesis, but the mechanisms of action as well as the net effect of this cytokine in atherosclerosis is far from clear." (PMID 29176764, 2017). "IL-27 plays an important role in inflammation and atherosclerosis pathogenesis with dual effects, both pro and anti-inflammatory." (PMID 28969085, 2017). "To further elucidate the role of IL-27 in atherosclerosis, we examined IL-27 levels in patients with carotid atherosclerosis, both systemically and within the lesion." (PMID 29176764, 2017). "Interleukin-27 (IL-27) is involved in different inflammatory diseases; however, its role in atherosclerosis is unclear." (PMID 29176764, 2017). "The lack of IL-27 receptor and IL-27 p28 subunit expression in animal models accelerates atherosclerosis, indicating an anti-atherogenic role for IL-27 by reducing recruitment of myeloid cells into atherosclerotic vessels." (PMID 25699211, 2015). "Our proteome analysis revealed an IL27-induced regulation of a variety of proteins which are involved in the inflammatory state of the endothelium as well as the development of atherosclerosis." (PMID 26663990, 2015). "Since these functions are fundamental characteristics of the early steps of atherosclerosis development, we propose not only a proinflammatory but also a proatherogenic role for IL27, which is in agreement with the pathway analysis of King and coworkers." (PMID 26663990, 2015). "Regarding our results, we therefore propose a model of a calprotectin reducing effect on IL27-mediated inflammation of the vascular endothelium in the context of atherosclerosis." (PMID 26663990, 2015). "Given the main effect of IL-27 is the regulation of the innate and adaptive immunity, it is most likely to be involved in atherosclerosis." (PMID 22911112, 2012). "Recent studies on cardiomyocytes and vascular endothelium have demonstrated mechanisms through which IL-27 could potentially modulate atherosclerosis." (PMID 41302192, 2025). "Thus, studies with cell cultures and animal models paint a complex picture of the role of IL-27 in atherosclerosis, which remains to be elucidated." (PMID 41302192, 2025).
atherosclerosis (continued). "IL-27 controls the development of inflammatory Th17 cells and might decrease inflammation in atherosclerosis." (PMID 39844544, 2025). "Likewise, in a model of angiotensin-mediated atherosclerosis, IL-27 was needed to overcome HSC quiescence and increase differentiation and output of mature myeloid cells." (PMID 39868131, 2025). "To determine whether the administration of recombinant IL-27 affects the initiation of atherosclerosis, we treated 6-week-old ApoE−/− mice with IL-27/anti-IL-27p28-Ab/PBS while they were fed a high-fat diet for 8 weeks." (PMID 36405994, 2022). "To determine whether the administration of recombinant IL-27 affects the progression of atherosclerosis, we treated ApoE−/− mice with IL-27/anti-IL-27p28 antibody/PBS for another 8 weeks after 8 weeks of western diet consumption." (PMID 36405994, 2022). "Our study indicates that IL-27 or adoptive transfer of IL-27 loaded tDCs may be a new therapeutic approach in atherosclerosis." (PMID 36405994, 2022). "Compared with the mice treated with PBS, the mice treated with IL-27 in the early stage of atherosclerosis exhibited a 33.7% reduction in the aortic sinus atherosclerotic lesion size (mean aortic sinus plaque area 415.3 ± 40 × 103 μm2 vs 275.2 ± 40 × 103 μm2, respectively; P = 0.03)." (PMID 36405994, 2022). "Thus, the purpose of this pilot study was to evaluate the potential utility of sirtuin 1, visfatin, and IL-27 as markers of early development of atherosclerosis or HF in young, asymptomatic women with T1DM and HD." (PMID 34439776, 2021). "Furthermore, knockout of IL-27 or IL-27 receptor in bone marrow-derived macrophages aggravates atherosclerosis and facilitates the activation of bone marrow-derived cells in the arterial wall." (PMID 34388961, 2021). "We did find an association between lipid parameters and IL-27 and sirtuin 1 levels in women with T1DM, which may lead to an increased risk of atherosclerosis." (PMID 34439776, 2021). "However, the subclinical atherosclerosis-associated plasmatic signature in the HIVneg population was different and marked with the upregulation of TNF-α and IL-27 and downregulation of CCL26 and IL-17C (p=0.02, 0.043, 0.011 and 0.021, respectively)." (PMID 33936102, 2021). "In addition, animal studies have demonstrated that all members of the IL-12 family are involved in the development of high-fat-diet-induced atherosclerosis, with IL-12, IL-23, and IL-27 promoting the process and IL-35 inhibiting it." (PMID 32322161, 2020). "Both the effects of IL-27R and IL-27 on atherosclerosis were reported." (PMID 32194399, 2020). "In atherosclerosis, increased expression of p28 and Ebi3 have been found in plaques, and elevated circulating IL-27 levels are reported in patients with coronary artery disease (CAD), associated with oxidized low-density lipoprotein (oxLDL) levels and disease severity." (PMID 29176764, 2017). "Our findings may suggest a role for IL-27 in clinical atherosclerosis, potentially mediating inflammatory effects." (PMID 29176764, 2017). "Several studies suggest an important role of Interleukin-27 in the development of atherosclerosis." (PMID 28969085, 2017). "Altogether, these studies suggest IL-27 could play a crucial role in the immunity and inflammation regulatory net in atherosclerosis." (PMID 28969085, 2017). "Our findings may suggest a role for IL-27 in clinical atherosclerosis, at least partly through its enhancing effects on LPS-mediated functions and NLRP3 inflammasome activation." (PMID 29176764, 2017).